GATA3 (GATA binding protein 3)
Diseases named in the same sentence as GATA3 in open-access papers (continued):
Sharing a sentence is not in itself a finding about the gene and the disease.
tumor (continued). "Furthermore, a reduction in GATA3 expression or its disappearance was observed in a portion of the tumor, an area with spindle cell proliferation, suggesting sarcomatous differentiation." (PMID 39896229, 2025). "Due to enhanced survival, greater migratory potential, and specific suppression of effector T cells, it is suggested that GATA3+ hTregs might promote a tumor-supportive environment." (PMID 41041322, 2025). "However, we observed that tumor driver genes such as GATA3 and ESR in DCIS were almost uniformly distributed spatially, but their corresponding SNVs were only present in the tumor." (PMID 40515555, 2025). "PTEN, a tumor suppressor regulating cell growth, was targeted by compounds with binding affinities ranging from −7.7 to −7.1 kcal/mol, while GATA3, a TF involved in immune regulation and cancer progression, exhibited stronger interactions with inhibitors scoring between −8.8 and −8.7 kcal/mol." (PMID 41476995, 2025). "In the immunohistochemical analysis, the tumor cells were positive for GATA-binding protein 3 (GATA3) and trichorhinophalangeal syndrome type 1 (TRPS1) but negative for HepPar1 and Glypican-3, which indicated that the tumor originated in the breast rather than the liver." (PMID 40994809, 2025). "Although rs1244159 itself was not directly linked to prognosis, its interaction with GATA3 expression highlights the importance of considering germline tumor biomarker relationships." (PMID 40650155, 2025). "Among these candidate genes, the transcription factor GATA3, a well-known lineage specific marker in breast and urothelial tissues, has garnered attention due to its dual role as a differentiation regulator and potential tumor suppressor." (PMID 40650155, 2025). "It has also been suggested that GATA3-positive expression may correspond with more regular ultrasound features, such as well-defined tumor margins and reduced vascular signals." (PMID 40881878, 2025). "High GATA3 expression is also associated with favorable clinical prognostic features, including lymph node negativity, lower tumor grade, older age at diagnosis, and negative human epidermal growth factor receptor 2 (HER2)." (PMID 40439821, 2025). "To assess the PCa tumour microenvironment for impaired immunity, we also performed a pilot RNA-expression analysis for PCa-associated immunological factors (IL1β, IL10, IL18, TNF-α, TLR4, GATA3, CD68)." (PMID 40430084, 2025). "The mutation frequency and tumour mutational burden (TMB) of the two groups were calculated using the maftools package in R. The mutation frequencies of PIK3CA, CDH1, GATA3, and MAP3K1 were higher in the “Low-risk” group compared to those of the “Low-risk” group." (PMID 41221278, 2025). "Interestingly, both GATA3–METH and GATA–LOFDEL groups of tumours were significantly enriched in the gene signature of mutated BRCA1." (PMID 40585280, 2025). "GATA3 deletions are very rare in urothelial cancer and unrelated to the tumor phenotype." (PMID 39979991, 2025). "Strategies to restore GATA3 expression or function in solid tumors could reprogram tumor cells towards a less aggressive phenotype, enhancing therapeutic responses and patient outcomes." (PMID 41514651, 2025). "Moreover, immunohistochemically, all four tumours exhibited varying expression of trophoblastic markers like GATA3, hPL, α-inhibin, PLAP, β-hCG, and p63, in addition to cytokeratin expression." (PMID 40413529, 2025). "The GATA3 positivity indicated the urothelial origin of the tumor." (PMID 40406259, 2025). "Immunohistochemistry (IHC) was performed to assess GATA3 expression in dermal tumor cells." (PMID 40856420, 2025). "Notably, the tumour suppressor gene GATA3 emerged as a primary target of functional inactivation through either loss-of-function mutations or DNMT3B-controlled hypermethylation, in a mutually exclusive manner." (PMID 40585280, 2025). "Moreover, GATA3 overexpression promoted LTR-Env-mediated tumor formation, whereas GATA3 knockdown suppressed it." (PMID 41585508, 2025).
tumor (continued). "GATA-3 staining was strongly and diffusely positive in tumor cells, confirming breast origin." (PMID 41556026, 2025). "Moreover, GATA3 orchestrates complex cross-talk between TAMs and tumor cells, facilitating epithelial-mesenchymal transition (EMT), chemoresistance, and overall tumor progression." (PMID 40330466, 2025). "In muscle-invasive carcinomas, GATA3 amplification was not linked to tumor aggressiveness or patient survival." (PMID 39979991, 2025). "GATA3 expression was assessed via immunohistochemistry (IHC) in 98 tumor tissues." (PMID 40650155, 2025). "By IHC, the tumor cells were diffusely positive for GATA3 and PAX8." (PMID 39469368, 2024). "This study concluded that basal tumours with KRT5/6, p63, and KRT14 expression had a better response to chemotherapy, while luminal tumours with active PPAR expression and activating mutations in FGFR3 showed expression of KRT20, FOXA1, and GATA3." (PMID 39594166, 2024). "CK7, CK20, and GATA3 are commonly used in pathology for tumor diagnosis and classification." (PMID 39943990, 2024). "The TNM stage, tumor differentiation, and metastasis after treatment were risk factors for the prognosis of SRCC patients (p < 0.05), while surgical treatment, chemotherapy, and positive GATA3 expression were protective for prognosis (p < 0.05)." (PMID 39316894, 2024). "Absence of GATA3/FOXA1 co-expression (GATA3-/FOXA1-) was associated with tumor extensive necrosis (P=0.001) after Bonferroni correction for multiple comparisons." (PMID 38425344, 2024). "In conclusion, our study revealed that the absence of GATA3/FOXA1 expression is linked to tumor extensive necrosis and poor prognosis in UTUC." (PMID 38425344, 2024). "Luminal tumours were (GATA3, FOXA1+), and basal/squamous tumours were (KRT5/6, KRT14+)." (PMID 39594166, 2024). "We then performed cologenic assays to further evaluate the sensitivity of the cells to PARPi and found that OLA slightly reduced the colony formation of Brca1+/+;Gata3+/+ tumor cells but significantly inhibited the colony formation of Brca1+/− or Gata3+/− tumor cells." (PMID 38627785, 2024). "Similarly, GATA3 showed increased positivity in normal duct and luminal tumor and decreased positivity in basal tumors." (PMID 39478117, 2024). "Additionally, tumor suppressiveness of GATA3 was detected in HCC through its direct regulation of slug expression, thereby interfering with the EMT process, cell proliferation, invasion, and migration." (PMID 39768217, 2024). "When the primary tumor of origin is unknown, supplementary markers can aid in the identification of tumors of mammary origin including GATA3 (binding protein), mammaglobin (lactoglobulin), and GCDFP15 (giant cystic disease liquid protein)." (PMID 39121246, 2024). "This substantiates the influential role of GATA3’s phase separation in tumor cell growth." (PMID 38531854, 2024). "In tumor tissue, GATA-3, paired box 8 (PAX8), and CD10 were positive, and ER was negative." (PMID 39589956, 2024). "Also, for cases with positive GATA3 expression, based on the intensity and percentage of tumor cell staining, the H score was determined, which ranged from 2 to 35, with an average of 10.6." (PMID 39118796, 2024). "Similarly, upregulated KIAA1429 downregulates the tumor-suppressing gene GATA3 by adding m6A modifications that prevent GATA3 pre-mRNA from binding to HuR." (PMID 38809498, 2024). "Furthermore, we provide the first evidence that silencing GATA3 in MDA-MB-453 cells enables AR to stimulate proliferation, supporting the concept that AR/GATA3 interactions are tumor suppressive even in this context." (PMID 38317241, 2024). "KTB42- HRasG12V + SV40-T/t cell-derived tumor was ERα−/GATA3−/FOXA1−, and CK8−/CK14−/CK19−." (PMID 37709737, 2023).
tumor (continued). "Further research revealed that miR-155-5p could target GATA-binding protein 3 (GATA3) in drug-sensitive tumor cells." (PMID 36839784, 2023). "As a consequence, GATA3 may function as a mediator for CAF invasion as well as attracting surrounding immune cells such as TAMs to promote tumor development and metastasis in HGSOC patients." (PMID 37039909, 2023). "GATA3 positivity was detected as brownish nuclear staining of tumor cells." (PMID 36737799, 2023). "Deletion of Fra1 or reconstitution of Gata3, but not reconstitution of c-Fos, in Gata3 deficient tumor cells inhibits EMT, preventing tumorigenesis and/or metastasis." (PMID 37353480, 2023). "Indeed, our previous analysis of CK5-expressing TNBCs suggested that GATA3 was expressed in 71% of the 115 cases tested, but only 23 cases (20%) expressed this protein in > 5% of the tumour cells." (PMID 37012444, 2023). "Furthermore, GATA3 acts as a constraint on the metastatic dispersion of tumor cells by impeding the epithelial-to-mesenchymal transition (EMT) process." (PMID 37900131, 2023). "Depletion of Gata3 in luminal tumor cells similarly regulates Fra1 and c-Fos in activation of EMT." (PMID 37353480, 2023). "One study reported on the use of GATA-3 to verify the site of tumor origin in two male dogs with triple-negative mammary carcinoma by employing its reported high sensitivity and specificity as a marker to identify primary and metastatic invasive breast carcinomas." (PMID 37483298, 2023). "Notably, we discovered that reconstitution of c-Fos in Gata3-deficient tumor cells promotes EMT and tumor cell growth." (PMID 37353480, 2023). "Consistent with this Th1 antigen–specific cytokine profile, mice vaccinated with the CD4 vaccine only had a significantly higher proportion of Tbet+CD4+ Th1 cells and significantly lower GATA3+CD4+ Th2 cell population within the tumor compared with mice vaccinated with the CD8 vaccine." (PMID 38063199, 2023). "The tumour was GATA3-, CK5-, CK14- and CK7-positive and TTF1-negative." (PMID 37760817, 2023). "If GATA3 immunohistochemical (IHC) expression differs between tumor grades, it could be useful in assessing biopsy specimens." (PMID 37629741, 2023). "Indirect validation of our approach was provided by the significant associations between high levels of progesterone receptor (PR), estrogen receptor (ER), androgen receptor (AR), GATA3 expression, and favorable tumor features as well as prolonged overall survival." (PMID 38137396, 2023). "Deletion of Fra1, but not reconstitution of c-Fos, in Gata3-deficient tumor cells inhibits EMT suppressing tumorigenesis and metastasis." (PMID 37353480, 2023). "Taking advantage of Gata3 and Brca1 deficient tumor cells lacking Gata3 and expressing high level of Fra1, we knocked out Fra1 in these cells by using the CRISPR/Cas9 system." (PMID 37353480, 2023). "The tumour cells were also positive for GATA3, E-cadherin, Pax-8, Succinate dehydrogenase B (SDHB) and Fumarate hydratase (FH), and negative for vimentin, Carbonic anhydrase 9 (CA9), CD10, P504s, CK20, TFE3, TFEB, HMB45, ALK and Forkhead box protein I1 (FOXI1)." (PMID 36816543, 2023). "Similarly, we also observed a similar phenomenon; we found that GATA3 over-expression indicated favorable prognosis, lower tumor grade, and lower tumor stage." (PMID 35647011, 2022). "GATA3 knockdown in A549 cells increased radiosensitivity of A549 cells and reduced tumor volume." (PMID 35993027, 2022). "IHC analysis revealed that Gata3 depleted tumors displayed significantly less Ki67 and more p18 positive cells than control tumors, indicating that Gata3 depleted tumor cells proliferate slower than control cells in vivo." (PMID 34976209, 2022). "While prior studies have demonstrated that GATA-3 is associated with genetically and clinically distinct subsets of T-cell lymphoproliferative neoplasms, the work presented here provides the first direct demonstration that GATA-3 is a bona fide proto-oncogene in these aggressive neoplasms." (PMID 36329027, 2022).
tumor (continued). "Furthermore, we discovered that depletion of Gata3 in MMTV-PyMT luminal tumor cells promotes basal differentiation and leads to development of BLBCs." (PMID 34976209, 2022). "Both p.H433fs and p.S410fs GATA3 mutations result in elongated protein isoforms (51 and 55 kD, respectively), with the primary tumor (HBCx-169) showing no GATA3 wild type protein expression." (PMID 35440675, 2022). "GATA3 is conventionally used as a tumor suppressor in early T-cell precursor ALL (ETP-ALL)." (PMID 36714653, 2022). "In addition, we demonstrated the immunohistochemistry (IHC) assay to monitor metastasis with the marker GATA3, which is often used for detecting urothelial or breast origin tumor." (PMID 35359350, 2022). "In vivo studies further show that GATA3 knockdown dramatically reduces tumor volume." (PMID 35846378, 2022). "Th2 cells (CD4+/GATA3+ cells) were also represented in the tumour areas, ranging from 10% to 25%." (PMID 33948980, 2022). "Strikingly, GATA3 knockdown combined with IR significantly suppressed A549 tumor growth." (PMID 35993027, 2022). "Our study indicated that repressing of GATA3/KLHL42 axis might be one critical function route of 5-FU inhibiting tumor progression." (PMID 36400759, 2022). "IHC markers like CK5/6 and GATA3 that are used in pathological routine could help to identify patients with basal and luminal tumor characteristics." (PMID 35783619, 2022). "GATA3 colored the nucleus light brown, indicating that the tumor was of breast origin." (PMID 35359350, 2022). "Interestingly, GATA3-positive tumours had higher levels of c-MYC and proliferation gene signatures than other PTCLs." (PMID 35681778, 2022). "Our study identifies, for the first time, SATB2 and GATA3 expression as features of Hyams’ grades 1–3 ONBs, expands the spectrum of SATB2 and GATA3-positive neoplasms, and suggests that Hyams’ grade 4 ONBs are not only clinically but also biologically different from low graded ONBs." (PMID 35522392, 2022). "The observation that Gata3 depletion in luminal tumor cells induces p18 with reduction of cell proliferation and tumor growth is consistent with our previous finding that p18 is a downstream target of GATA3 restraining luminal cell proliferation and tumorigenesis." (PMID 34976209, 2022). "GATA3 was highly expressed in patients with low-grade and low tumor stages." (PMID 35647011, 2022). "We found more PU.1+ T cells in the tumour tissue than GATA3+ cells." (PMID 35793807, 2022). "However, the immunohistochemical features of the tumor (positive for ER, PR, and GATA3) suggested that this tumor was derived from the mammary gland." (PMID 36528621, 2022). "Of particular interest, the expression of GATA3, a critical transcription factor involved in multiple cell processes including T-cell differentiation, tumor progression and metastasis, significantly increased in lncRNA-IUR1 knockdown K562 cells compared with the controls." (PMID 34980123, 2022). "In view of the fact that the regulatory factors of some embryonic development stages are also closely related to tumorigenesis, it is speculated that GATA3 might participate in the tumor initiation or progression of PRNRP." (PMID 36002896, 2022). "Moreover, the transcription factor GATA3 was identified as a tumor suppressor that inhibits proliferation of cancer stem cells." (PMID 33235291, 2021). "Moreover, previous studies have shown the prevalence of PD-L1-expressing CD8+ cells in the GATA3/CR5/6-negative immune microenvironment along with the moderate to high expression of the biomarker by tumor cells." (PMID 34576020, 2021). "Other clinicopathological characteristics that were associated with GATA3 mutation status in this patient cohort are the following: pathologic tumor size was significantly different between patients with GATA3 mutant tumors compared to patients with wild-type GATA3 tumors (p = 0.01)." (PMID 33462316, 2021).
tumor (continued). "In light of the present study, we hypothesise that the accumulation of DNA damage generated during chemotherapy recruits GATA3, allowing GATA3-positive tumours to maintain mitochondrial fitness and evade chemotherapy induced apoptosis." (PMID 34099719, 2021). "Furthermore, in one of these two cases, GATA3 staining was strongly positive in approximately 10% tumor cells." (PMID 34441384, 2021). "Epigenetic inactivation of GATA3 may provide a new clue to the peculiar biology of this rare neoplasia." (PMID 33382535, 2021). "We conclude that expression of a single biomarker (e.g., HNF1β and GATA3) should not be interpreted as diagnostic of a particular tumor type without taking into consideration the histology." (PMID 33986807, 2021). "Our results suggested the importance of GATA3 in tumor size in the TCGA dataset." (PMID 33462316, 2021). "GATA3 expression showed a significant association with tumour histology, with higher expression in UC as opposed to VH and UCDD, both in individual studies and in our meta-analysis." (PMID 34690921, 2021). "CTLA4, Tim3, Foxp3, GATA3, CD127, TCRab and TIGIT increased in cluster 17 of CD3+ T cell in patients with LC, of which CTLA4 expressed in tumour CD8 T cells associated with PD‐1‐mediated T‐cell dysfunction and efficacy of the checkpoint block immunotherapy in cancers." (PMID 34841705, 2021). "According to our finding, GATA3-mutants had larger tumor size that it may be due to the down-regulation of CSN1S1." (PMID 33462316, 2021). "Disrupting Gata-3 in naïve CD8+ T cells improved T cells anti-tumor function." (PMID 34095145, 2021). "Consistent with the findings derived from tumor tissues, primary p18mt;Brca1+/- and p18mt;Gata3+/- tumor cells also exhibited a typical mesenchymal-like morphology with a high level of EMT markers, whereas, epithelial-like morphology were observed in p18mt and MMTV-PYMT tumor cells." (PMID 34373738, 2021). "Interestingly, very weak Brca1 and Gata3 expression were observed in less than 10% of p18mt;Brca1+/- lung metastatic tumor cells, while Gata3 was barely detectable in p18mt;Brca1+/- lung metastasis." (PMID 34373738, 2021). "However, most of the tumor cells with GATA3 and PAX2 expression demonstrated nuclear immunoreactivity for ER and PR with moderate-to-strong staining intensity." (PMID 34441384, 2021). "Two mice that received p18mt;Gata3+/- tumor cell transplants died of lung metastasis in 4 weeks." (PMID 34373738, 2021). "Therefore, GATA3 expression was higher in BCs with less aggressive clinico-pathological characteristics, such as grade 1 and grade 2, smaller tumor size, and lower stage than in BCs with worse prognosis characteristics." (PMID 33800667, 2021). "Moreover, expression of GATA3, IL-10, and IL-10R was also increased, indicative of a generally immunosuppressive tumor microenvironment in BCG failure." (PMID 33672843, 2021). "Moreover, GATA3 can activate the downstream molecule miR-29b that can further inhibit the synthesis of proteins required for tumor metastasis." (PMID 34262865, 2021). "Seventeen tumors (68.0%) were at least moderately positive for GATA3 in ≥25% of tumor cells." (PMID 34829389, 2021). "We found MUC2 over-expression in GATA3-mutant tumor than normal samples." (PMID 33462316, 2021). "Interestingly, tumour stage, grade and pre-operative therapy significantly affected GATA3 positivity (p-value for mixed-effects model, p=0.0409, p=0.0056, p=0.0006, respectively)." (PMID 34690921, 2021). "There is some evidence that GATA3-dominant hPTCL affect the tumor microenvironment by driving macrophages toward an alternative, suppressive phenotype which may contribute to poor outcomes." (PMID 32038991, 2020). "In addition, GATA3 has also been proved to promote the differentiation of T cells into Th2 cells by increasing cell effector Th2, thus affecting the immune response of tumor cells." (PMID 32538432, 2020).